KDM6A (lysine demethylase 6A)
Diseases named in the same sentence as KDM6A in open-access papers (continued):
Sharing a sentence is not in itself a finding about the gene and the disease.
cancer (continued). "NK cells kill cancer cells through the secretion of the pore-forming protein perforin and granzymes, we next examined whether the resistance of KDM6A-KO cells to ADCC was due to attenuated NK activity." (PMID 38355622, 2024). "KDM6A is an essential gene that impacts developmental processes and cancer progression." (PMID 38791111, 2024). "Genes encoding KDM6A, KMT2D and EP300 are highly mutated in human cancers." (PMID 37410700, 2023). "Among the constitutive escapees, there are the highly biomedically-relevant genes DDX3X, KDM5C and KDM6A, whose escape may contribute to lower cancer incidence in females than males." (PMID 36802379, 2023). "KDM6A plays various roles as a histone demethylase during cancer development." (PMID 37846441, 2023). "The low rate of intersection might be attributed to either the wild-type vs. truncated KDM6A function or the different characteristics of these two cancer cell lines." (PMID 36980177, 2023). "KDM6A, KMT2D, and p300 are important proteins implicated in cancer and developmental syndromes." (PMID 37410700, 2023). "The demethylase KDM6A/UTX is frequently mutated in cancer and these mutations are not confined to the JmjC domain, so that demethylase-independent effects are possible." (PMID 35406676, 2022). "Quantitative gene transcript analysis at early time points (from 30 min to 24 h) showed statistically significant induction of various histone demethylases such as JARID1A, JARID2, JMJD1A, and KDM6A/B in all the three cancer cell types grown in detached conditions." (PMID 35186918, 2022). "Interestingly, many genes related with epigenetic regulation of enhancer activity are frequently mutated in cancer, such as MLL3/4, p300, CBP, lysine demethylase 6A (KDM6A, also named as UTX) and lysine demethylase 5C (KDM5C)." (PMID 36192394, 2022). "The KDM6A were also found to be associated with estrogen receptor (ER) and retinoic acid receptor (RAR) upon ligand treatments, including estrogens and retinoic acid, which is necessary for cellular differentiation, cancer tumorigenesis and metastasis." (PMID 34950587, 2021). "Other studies support KDM6A in having sex-specific roles in normal biology and cancer." (PMID 34220955, 2021). "KDM6A is a tumor suppressor gene in different cancers, including lung SqCC." (PMID 33407425, 2021). "Under hypoxia, effective concentration of α-KG is decreased, and the 2-HG level is increased via metabolic reprogramming, thus contributing to the inhibition of α-KG-dependent KDM6A, which is related to cellular heterogeneity, cancer resistance, and progression." (PMID 34950587, 2021). "Immunohistochemistry was used to visualize loss of the cancer driver KDM6A in formalin-fixed paraffin-embedded (FFPE) normal human colonic epithelium." (PMID 33895166, 2021). "The KDM6A gene is located on the X chromosome, encodes a histone H3 lysine 27 (H3K27)−specific demethylase, and carries somatic loss-of-function mutations in various types of cancer." (PMID 34029637, 2021). "KDM6A also has been shown to be overexpressed and exert different roles in multiple human cancers." (PMID 34950587, 2021). "Whether the KDM6A suppresses or promotes tumorigenesis and progression depends on the cancer type and its interacting transcription factors." (PMID 34006303, 2021). "Gender bias in KDM6A inactivation has been reported in some cancer types." (PMID 34950587, 2021). "Furthermore, knockdown of KDM6A decreases cancer cell proliferation, invasion, and lung colonization." (PMID 33003334, 2020). "Cancer types with alteration at KDM6A in at least 2% of cases are shown." (PMID 33003334, 2020). "Cancer cells that harbored mutations in the PHD domain of MLL3 or lacked BAP1 showed reduced recruitment of UTX/KDM6A to gene enhancers, with no reduction in the levels of the repressive H3K27me3 mark." (PMID 31221981, 2019).
cancer (continued). "To identify a reliable marker of hypoxia linked to KDM6A status, we retrieved PDAC data from the ICGC and The Cancer Genome Atlas (TCGA) databases and found that in both cohorts the hypoxia‐related gene SCL2A1 (encoding for GLUT1) was significantly upregulated when KDM6A was inactive." (PMID 30306561, 2019). "Interestingly, chromatin regulators such as the histone methyltransferase MLL2, the chromatin remodeling gene ARID1A, the histone demethylase KDM6A and the histone acetyltransferase EP300 were frequently mutated in this cancer type." (PMID 25473433, 2014). "Therefore, KDM6A has at least two independent, yet complimentary, mechanisms for shaping the epigenetic landscape in cancer." (PMID 24622842, 2014). "The H3K27 demethylases KDM6A and KDM6B have also been implicated in carcinogenesis and the finding that KDM6B is the major mediator of OIS further supports the involvement of these enzymes in cancer formation." (PMID 23673719, 2013). "Among the most important histone demethylases associated with the development of cancer are LSD-1/KDM1A, and members of the Jumonji family JARID1A-1C/KDM5A-5C, JHDM1B/KDM2B, JMJD2C/KDM4C, JMJD2A/KDM4A, JMJD3/KDM6B, and UTX/KDM6A, which will be analyzed in detail in the following paragraphs." (PMID 24280700, 2012). "Notably, we detected aberrant expression of XIST, the essential X-chromosome-inactivation lncRNA that is not normally expressed in males, and upregulation of genes known to escape X-inactivation, including male-biased cancer-related genes KDM6A, DDX3X, KDM5C, and ZRSR2." (PMID 42070154, 2026). "Targeting KDM6A/B also might improve the anti-cancer effects of cisplatin." (PMID 40940894, 2025). "Thus, like in ATRX, KDM6A, and H3K27M, EZHIP alterations are associated with male-skewed cancers." (PMID 38949020, 2024). "They identified KDM5C and KDM6A as the EXITS (escape from X-inactivation tumor suppressors) genes and suggested that mutations in EXITS genes could underlie the male predominance in various cancers." (PMID 38982123, 2024). "assessed KDM6A, a member of the mixed-lineage-leukemia (MLL2) H3K4 methyltransferase complex, and reported that expression of KDM6A protein was higher in NSCLC tissues than in corresponding para-cancer tissues and that higher expression was associated with poor prognosis." (PMID 37817767, 2023). "Notably, BLAC scores of cancer-associated somatic mutations in KDM6A show higher elevation than germline or other noncancerous somatic mutations." (PMID 35753349, 2022). "In such examples, UTY could be functional, but UTY mutations can also occur, and complete loss of the Y chromosome is not uncommon in males with a KDM6A mutation in cancer." (PMID 35406676, 2022). "This review specifically addresses the role of H3K27 demethylation in various diseases, including cancer, inflammatory diseases and viral and bacterial infections, and the therapeutic potential of inhibiting this demethylation, focusing on the small-molecule KDM6A/B inhibitor GSK-J4." (PMID 35915507, 2022). "Taken together with the attenuated levels of KDM6A in stem-like cells, we suggest that low overall KDM6A expression and/or activity may be a contributing factor in the establishment of the relative quiescence manifested by normal and cancer stem cells." (PMID 29029452, 2017). "Deregulation of the H3K27me3 balance that is governed by the coordinated enzymatic activities of EZH2 and KDM6A/KDM6B leads to differentiation defects and cancer." (PMID 41085408, 2025). "Importantly, while KDM6A mutations are relatively rare in HNSCC, we observed significantly elevated KDM6A-pSer829 levels in clinical specimens, suggesting that post-translational modification represents a predominant mechanism of KDM6A regulation in this cancer type." (PMID 41184251, 2025). "Next, the expression profiles of CD44, FGF2, FGF10, KDM6A, FN1, and MMP2 were evaluated using the OcoDB database across different clinical stages, age groups, and racial categories in cancer patients." (PMID 39833941, 2025).
cancer (continued). "We therefore evaluated the expression of KDM6A and KDM6B demethylases in a panel of cancer cell lines." (PMID 41085408, 2025). "Lysine demethylase 5C (KDM5C), KDM6A, and ATRX chromatin remodeler (ATRX) are X-escapees that directly regulate epigenetics and play substantial roles in cancer protection." (PMID 38949020, 2024). "Overall, however, inhibiting KDM6A/B with the small-molecule inhibitor, GSK-J4, not only suppresses the abnormal growth of cancer cells but confers upon them increased sensitivity to chemotherapeutic agents." (PMID 35915507, 2022). "Overall, we observed that reducing the KDM6A/B activity significantly reduces the sphere-forming capacity and invokes apoptosis in ECM-detached cancer cells." (PMID 35186918, 2022). "To conclude, it is apparent that the H3K27me3-specific demethylases KDM6A and KDM6B play complex, occasionally contrasting, roles in the pathogenesis of various diseases, ranging from cancer to inflammatory, autoimmune and infectious diseases." (PMID 35915507, 2022). "Overall, we found that matrix detachment modulates the epigenome during anoikis, inducing KDM6A/B that positively regulates the expression of SOX2, CD44, and HIF1α to regulate survival and stemness of cancer cells." (PMID 35186918, 2022). "EZH2 and KDM6A / B play the opposite role in catalyzing the methylation of H3K27, but they can also exhibit cancer-promoting activity." (PMID 34001062, 2021). "Based on intensive studies across a broad spectrum of tumors, the functional roles of KDM6A and KDM6B were inconsistent in the same type of cancer." (PMID 34950587, 2021). "Several KDMs are part of protein complexes like the COMPASS complex that contains KDM6A as well as methyl transferases MLL2 and MLL3 that regulate gene transcription in certain cancers." (PMID 34220955, 2021). "The overexpression of KDM6A only slightly increased the ARHGDIB levels in MKN-45 cells, indicating that KDM6A regulates ARHGDIB in a cancer type-specific manner." (PMID 34006303, 2021). "In three patients, we detected fusions involving a cancer-related gene, such as STK11 and KDM6A, quoted as altered in MPM in the Cosmic database (release v91), or TFG reported in fusions in other cancers." (PMID 34261524, 2021). "Although aspects of their biochemical regulation still remain to be determined, demethylase enzymes like KDM6A and KDM6B are often genetically inactivated in various types of cancers." (PMID 33003334, 2020). "Surprisingly, KDM6B, in contrast to KDM6A, acts as an oncogene in NOTCH1 overexpressing T-ALL cancer." (PMID 33003334, 2020). "Whole-exome sequencing analyses of ccRCC revealed that in addition to VHL, JARID1C/KDM5C, UTX/KDM6A, and SETD2 (H3K36 methyltransferase) were new cancer genes in ccRCC61." (PMID 31221981, 2019). "Inverse regulation of KDM6A/UTX and the paralogous histone demethylase KDM6B/JMJD3 has been observed in other cancers." (PMID 30987376, 2019). "The results confirmed that alterations involving RB1 and NFE2L2 were enriched in basal cancers, whereas alterations involving FGFR3 and KDM6A were enriched in luminal tumors." (PMID 29977169, 2018). "In these cancers, HPV oncogene expression similarly dysregulates expression of key regulators of H3K27me3, including members of PRC2 and the demethylases KDM6A and KDM6B." (PMID 29069809, 2017). "The reported fractions of cancers with negative or reduced KDM6A protein in the four studies were 25%, 30%, 69%, and 78%." (PMID 40723241, 2025). "Strategies to target cancers with ARID1A and KDM6A deficiency are not as mature as those targeting the PI3K/AKT/mTOR pathway; however, several recent promising results have been reported, offering hope for future research." (PMID 40723241, 2025). "Indeed, by phenotyping tumors according to relevant gene set expression scores, we show that RNA VAF identifies instances of possible driver-passenger misclassification events within the cancer genes EGFR and KDM6A." (PMID 40514689, 2025).
cancer (continued). "Thus, while the H3K27 methyltransferase EZH2 consistently supports cancer stemness and CSC-mediated oncogenesis, the role of H3K27 demethylases such as KDM6A is highly context dependent." (PMID 40744921, 2025). "It has been shown that the participation of KDM6A in cancer progression is not restricted to its enzymatic activity but to a demethylase-independent function." (PMID 41085408, 2025). "Lysine demethylase KDM6A (also known as UTX) belongs to the KDM6 family of histone H3 lysine 27 (H3K27) demethylases, which plays critical roles in homeostatic gene expression, cell differentiation, development and cancer." (PMID 37410700, 2023). "Notably, in vitro and in vivo studies revealed that ibuprofen diminished cancer cell metastasis, stemness properties, and cancer cell chemoresistance through a reduction in HDAC and histone demethylase KDM6A/B expression in a COX2-dependent manner." (PMID 35267528, 2022). "Compared to Del-c1 and c3, the majority of cancer genes were deleted by DEL-c2, such as CDKN2A (207/528), FHIT (133/528), KDM6A (42/528), RB1 (27/528), FAT1 (23/528), NFE2L2 (13/528), ERBB4 (20/528), CUL3 (11/528), PTEN (9/528), ZNF750 (13/528) and NOTCH1 (8/528)." (PMID 36272974, 2022). "Additionally, the expression of KDM6A and 6B was elevated in primary HNSCC, and KDM6A expression was significantly increased in grade 4 carcinomas." (PMID 35326475, 2022). "Accordingly, we are accumulating evidence that transcriptional differentiation programs governed by KDM6A/UTX can enforce and safeguard cellular identity in several cancer types, thereby hindering highly aggressive cancer types by blocking epigenetic roads to de-differentiation." (PMID 34153035, 2021). "Moreover, like KDM6A, KDM6B interacts with ER or RAR in the presence of estrogens or retinoic acid, and regulates the proliferation and differentiation of cancer cells." (PMID 34950587, 2021). "Given that the imbalance between KDM6A and EZH2 expression appears to sensitize many cancers to epigenetic inhibitors, resetting epigenetic balance could be useful in combination approaches." (PMID 34950587, 2021). "Searching the Cancer Cell Line Encyclopedia (CCLE) we found significantly lower levels of expression of several histone demethylases (KDMs), including KDM6A and KDM6B, in SMARCA4def compared with MYCamp cells or with LC cells that are wild type for SMARCA4 and MYC." (PMID 34262032, 2021). "We noticed that some of the SE-associated genes repressed by GSK-J4 treatment are well-known critical regulators of cancer cell stemness, such as ID126, 27 and TERT28, and further confirmed their downregulation by GSK-J4 or shRNAs targeting KDM6A or KDM6B in two CRC cell lines." (PMID 32929331, 2020). "Currently, the increasing trend of documents showed the essential contribution of histone demethylases such as JARID1, KDM4, LSD1, KDM6B, KDM6A, KMD3, KDM5, and Jumonji domain–consisting of protein 6 (JMJD6) to the cancer stem cell phenotype in several kinds of cancers." (PMID 32280305, 2020). "Importantly, distorted H3K27me3 landscape due to alterations in PRC2 subunits and two KDM6 enzymes (KDM6A or UTX, KDM6B or JMJD3) has been observed in the vast majority of human cancers 11-13." (PMID 32929331, 2020). "Whether H3K27 demethylases including KDM6A, KDM6B and KDM7A play an oncogenic or anti-oncogenic role in cancers is under active investigation." (PMID 28717873, 2018). "Thus, targeting KDM6A and/or disrupting the interaction between KDM6A and SND1 could represent a promising therapeutic strategy for cancer treatment and overcoming the chemoresistance bottleneck." (PMID 38850159, 2024). "Regardless of the potential ways to improve the mathematical analysis of this data, there is a clear relationship between KMT2D and KDM6A that did not happen by chance and extends beyond the scope of altered chromatin modification in cancer and into those of known developmental disorder KS." (PMID 35073341, 2022).
cancer (continued). "Ubiquitously transcribed tetratricopeptide repeat on chromosome X (UTX)—also known as KDM6A—is a histone demethylase that targets di- and tri-methylated histone H3 lysine 27 (H3K27); it is involved in embryonic development, tissue-specific differentiation, and cancer growth." (PMID 34465286, 2021). "For instance, in glioblastoma cells, the demethylases KDM6A/B, which target H3K27, are required for the maintenance of a subpopulation of quiescent cancer stem cells and their pharmacological inhibition with GSKJ4 selectively targets slow-cycling cancer stem cells." (PMID 33339101, 2020). "The trend is not as clear for demethylase, but we note that KDM5B, which removes the activating mark H3K4me3, is significantly overexpressed in five of the eight cancer types studied and never repressed, while the H3K27me3 demethylases KDM6A/B are repressed in most cancer types." (PMID 25484917, 2014). "As a result, it can be stated that the KDM6A overexpression induces the expression of ZO1, which may be effective in the EMT process and proliferation by affecting the process of tight junctions and cell–cell junctions and also reducing the migration of cancer cells." (PMID 41244070, 2025). "However, most cancer cells still express the non-mutant KDM6A." (PMID 41184251, 2025). "Whereas enzymatic roles of KDM6A and KDM6B are undisputed in cancer cells, non-enzymatic scaffolding roles for large complexes of all KDM6 members have been recognized." (PMID 34950587, 2021).
infection (6 papers, 2017 to 2025). The state of being infected such as from the introduction of a foreign agent such as serum, vaccine, antigenic substance or organism. "Although Kdm6a mutations have been associated with B cell cancers, its impact on humoral responses to infection and vaccination are only beginning to be assessed." (PMID 38486287, 2024). "Here, we demonstrate that the histone demethylase KDM6A promotes infection of diverse coronaviruses, including SARS-CoV, SARS-CoV-2, MERS-CoV and mouse hepatitis virus (MHV) in a demethylase activity-independent manner." (PMID 37410700, 2023). "KDM6A was depleted by infection with a lentiviral shRNA expression vector, depletion was verified by qRT-PCR, and cell viability was assessed." (PMID 28968467, 2017). "We next asked whether KDM6A/KMT2D/p300 axis is required for infection of other coronaviruses." (PMID 37410700, 2023).
metabolic disease (6 papers, 2021 to 2025). A congenital disorder (due to inherited enzyme abnormality) or acquired (due to failure of a metabolically important organ) disorder resulting from an abnormal metabolic process. "Most recently, the inhibition of Kdm6 family members with GSK-J4 was shown to abate nephropathy progression in diabetic db/db mice, suggesting that Kdm6a is also involved in the progression of metabolic diseases." (PMID 33303977, 2021).
adenocarcinoma (4 papers, 2019 to 2024). A common cancer characterized by the presence of malignant glandular cells. "In total, putative actionable genomic targets (FGFR2, BRAF-V600E, MTOR, NRAS, and KDM6A) were identified in 35% of the cases by OncoKB search, an important finding given the high number of fluent transitions from high-grade IEN to adenocarcinoma at the time of diagnosis (14/17 cases)." (PMID 34205964, 2021).
Kidney Diseases (3 papers, 2013 to 2023). "The causes of KDM6A upregulation in kidney disease are uncertain." (PMID 37655466, 2023). "These limitations notwithstanding, there has been significant recent interest in the roles that KDM6A may play in CKD and in the possibility of therapeutically targeting histone modifying enzymes to alter the natural history of kidney disease." (PMID 37655466, 2023). "Although, in comparison to sham-operated male mice as a point of reference, higher tubule cell Kdm6a levels do not indicate a major role for KDM6A in kidney disease pathogenesis, this does not exclude an influence of constitutively expressed KDM6A on the natural history of disease." (PMID 37655466, 2023).